CTSB (cathepsin B)
Diseases named in the same sentence as CTSB in open-access papers (continued):
Sharing a sentence is not in itself a finding about the gene and the disease.
tumor (continued). "Lysosomal cysteine cathepsins (CTSL and CTSB) are degradative enzymes playing a pivotal role in tumor invasion and metastasis." (PMID 31824841, 2019). "CTSB secretion into the tumor’s extracellular microenvironment can initiate several proteolytic cascades, including that leading to TGF-β activation." (PMID 30796200, 2019). "We have shown that CTSB knockdown slows tumor growth and improves response to VEGFR TKI therapy by mechanisms consistent with an effect on ALDH1-expressing CSCs." (PMID 30796200, 2019). "Research into the role of cathepsin B and cathepsin D in tumorigenesis, so far, has mainly focused on their independent influence on tumor invasiveness." (PMID 30949483, 2019). "The accumulation of collagen was accompanied by a strong decrease of the expression and activity of the protease cathepsin B. Overexpression of cathepsin B in ECs prevented the capability of archazolid to increase the adhesion of tumor cells onto ECs." (PMID 30204757, 2018). "Lysosomal protease-sensitive peptide linkers: Tumor cells have higher expression of lysosomal proteases like cathepsin B than normal cells." (PMID 29642542, 2018). "Lysosomal enzyme of CTSB, an overexpressed and secreted enzyme in tumor endothelial and epithelial cells, is one of targets that are frequently used in the development of enzyme-triggered nanomedicine." (PMID 29925404, 2018). "Cathepsin B-sensitive peptide linker conjugated ADCs selectively binds to and get internalized into tumor cells via receptor mediated endocytosis." (PMID 29642542, 2018). "MMP-2/9 and cathepsin B are proteolytic enzymes present at elevated levels in cancer cells known to participate in human tumor invasion and metastasis." (PMID 29765474, 2018). "A short peptide of GFLG linker was used as hydrophobic tails, which not only facilitated to load saracatinib to obtain stable NPs but also subjected to CTSB cleavage so as to release saracatinib in tumor tissues with acidic extracellular pH feature." (PMID 29925404, 2018). "The EHU is designed so as to be a substrate for proteases overexpressed in the targeted tumor microenvironment (i.e cathepsin B)." (PMID 29765474, 2018). "After secretion,cathepsin B attached to the tumor cell surfacethrough the annexin II heterotetramer, andmoved to lipid rafts of tumor cells where itcould come into contact with serine proteasesand matrix metalloproteinase." (PMID 28670517, 2017). "Tumour cells have increased membrane and secreted levels of cathepsin B, which is an attribute of their invasive phenotype." (PMID 29065110, 2017). "We also reported cathepsin B-specific cleavable peptide conjugated metabolic precursor for in vivo tumor-specific fluorescence imaging." (PMID 29192289, 2017). "The excess secretion of CtsB by different types of cells present in TME including tumor cells, tumor-associated macrophages (TAM) and fibroblasts, makes them potent cancer-specific targets." (PMID 28492519, 2017). "It was found that molecules related tomesenchymal cells (vimentin and transglin), in addition to those related to tumor aggressiveness with potential secretory behavior (e.g. cathepsin B) were among differentiallyexpressed proteins." (PMID 28670517, 2017). "An increase in the CTSB enzymatic activity in tumor cells treated with SAHA or other HDAC inhibitors has been reported, typically in association with apoptotic programmed cell death and autophagy." (PMID 28881816, 2017). "Our findings showed that targetable azido group generation of cathepsin B-specific metabolic precursor was clearly interrelated with cathepsin B-activity of the tumor cells in vitro cell culture system and in vivo tumor-bearing mice." (PMID 29192289, 2017).
tumor (continued). "Previous studies have also shown a tumor-promoting role for CAFs via IL-6 secretion and an association between IL-6 secretion and upregulation of ECM-degrading enzymes (e.g., cathepsin B, MMPs, and uPA)." (PMID 28506312, 2017). "For example, cytotoxic chemotherapy drugs can increase tumour expression of ADC-catabolising cathepsin B." (PMID 29065110, 2017). "Increased protease activity, including CTSB’s, in solid tumours, derives not only from the tumour mass, but also from the cells surrounding the tumour, with relevance in carcinogenesis and tumour metastasis." (PMID 29101342, 2017). "The identified differentially expressed proteins were related to mesenchymal cells (vimentin and transglin), or related to tumor aggressiveness with a potential of secretory behavior (e.g. cathepsin B)." (PMID 28670517, 2017). "Nitroxoline, a known antimicrobial agent, is a potent and selective inhibitor of cathepsin B, hence reducing tumor progression in vitro and in vivo." (PMID 28938624, 2017). "Cystatin SN (CST1), a known inhibitor of cathepsin B (CatB), has important roles in tumor development." (PMID 28383558, 2017). "Colorimetric in situ hybridization demonstrated the presence of mRNA transcripts coding for cathepsin B and cathepsin D within the tumor cells (pink, arrows) in the IDHWGB samples." (PMID 28611989, 2017). "Contrary to initial expectations, cathepsin B expression was observed not only in tumor cells, but mostly in TAM." (PMID 29244745, 2017). "Cathepsin B has additionally been thought to cleave anti-apoptotic proteins, such as Bcl-2, Bcl-xl and Bak, resulting in deregulation of tumour cell apoptosis." (PMID 28146084, 2017). "Accordingly, to study the effect of compound 17 on tumor cell migration and invasion in vitro, we selected cell lines of different origins, all expressing high levels of cathepsin B." (PMID 28938624, 2017). "We have recently shown that paracrine IL-6 signaling between DCIS cells and CAFs facilitates tumor cell growth and migration in part through cathepsin B-mediated ECM degradation." (PMID 28506312, 2017). "Various studies have suggested that cathepsin B participates in the pathology of carcinomas, and it is present at increased levels in advanced tumor stages." (PMID 28097424, 2017). "After partial extracellular degradation ECM fragments are internalized to tumor cells and completely degraded in lysosomes by cathepsin B and other peptidases." (PMID 28460472, 2017). "We have demonstrated that low molecular weight inhibitors of cathepsin B, able to inactivate both intra- and extracellular fractions of cathepsin B, effectively impair tumor progression." (PMID 28460472, 2017). "The diagnostic and prognostic significance of increased cathepsin B (CTSB) and cathepsin D (CTSD) concentration in the serum of cancer patients were evaluated for some tumor types." (PMID 26995190, 2016). "At the end of the study day 21, tumor weight of the control group (1.30 ± 0.07 g) was only 75 % of the MHCC-97 L/CTSB group (1.96 ± 0.06 g)." (PMID 26896959, 2016). "Cathepsin B is an important protease that regulates tumor cell invasion, and lysosomes proximal to the plasma membrane facilitate the release of cathepsins to the extracellular environment." (PMID 27105540, 2016). "It has been proposed that peripheral lysosome localization promotes increased cathepsin B secretion, localized extracellular matrix degradation, and tumor cell invasion." (PMID 26784896, 2016). "In the TNBC cohort, both interactors significantly correlated with expression levels of cathepsin B, c-Met and the tumor grade." (PMID 27286449, 2016). "In particular, it was demonstrated that acid extracellular pH induces lysosomal movement toward to cellular periphery and successive lysosomal exocytosis of cathepsin B, promoting protease-dependent tumor invasion." (PMID 27548222, 2016). "Tumor formation assay in nude mice was used to analyze the effect of CTSB on the tumorigenicity of HCC cell lines." (PMID 26896959, 2016).
tumor (continued). "Complexes of uPAR and uPA significantly correlated with IGF1R (p = 0.0032), cathepsin B and D (p ≤ 0.0001, respectively) expression and inversely with the tumour size (p = 0.0065)." (PMID 27502396, 2016). "High CTSB expression was significantly correlated with advanced clinical staging, histological grade, and tumor recurrence." (PMID 26896959, 2016). "Several studies have found that Cathepsin B (CTSB) is up-regulated in many tumor types and facilitates tumor progression." (PMID 26896959, 2016). "From these results, it appears that the tumor-specific cytotoxicity of pyrimethamine is mediated by the enhancement of cathepsin B activity in HCC cells." (PMID 27756242, 2016). "Our study demonstrated that niclosamide reduced acidic-triggered cathepsin B secretion, an event thought to be important for tumor invasion." (PMID 26784896, 2016). "Particularly, we have shown that several common features of the solid tumor microenvironment, hepatic growth factor (HGF), and acidic extracellular (pHe) trigger lysosome outward movement, accompanied by increased cathepsin B secretion and tumor cell invasion." (PMID 26784896, 2016). "The interactions of uPAR with Cyr61 significantly correlated with expression levels of tumor-promoting biomarkers including plasminogen (p=0.0014), cathepsin B (p=0.032), c-Met (p=0.0192) as well as with the tumor grade (p=0.02)." (PMID 27286449, 2016). "In this regard, inhibiting anterograde lysosome trafficking by overexpression of RILP results in reduced levels of secreted cathepsin B and tumor cell invasion." (PMID 26784896, 2016). "A number of clinical studies have been performed to evaluate the diagnostic and prognostic significance of elevated CTSB and CTSD concentrations in tumor cytosols." (PMID 26995190, 2016). "The mapping resolution, which approaches the single‐cell level, highlights CTSB +ve and −ve regions within a single tumor resection specimen." (PMID 26197973, 2015). "Previously, we reported an established antibiotic nitroxoline as a potent and selective inhibitor of cathepsin B. In the present study, we elucidated its anti-tumor properties in in vitro and in vivo tumor models." (PMID 25848918, 2015). "Tissue from this patient displayed an increased CTSB expression in the tumor region compared to the healthy region." (PMID 26197973, 2015). "Porous silicon nanoneedles can map Cathepsin B activity across normal and tumor human esophageal mucosa." (PMID 26197973, 2015). "This also has implications for the situation in vivo, since many cancer types contain increased levels of proteases in their tumor environment (including increased levels of cathepsin B) and this correlates with tumor progression and metastasis." (PMID 26712782, 2015). "For example, selective release of CtsB in response to different signals in different contexts leads to either tumor growth or apoptosis." (PMID 25738962, 2015). "Tumor and endothelial cell lines with high levels of active cathepsin B were selected for functional analysis of nitroxoline in vitro." (PMID 25848918, 2015). "The plasma of tumour‐bearing Apc580S/Δ mice was screened by mass spectrometry, and cathepsin B and D were found to be elevated compared with control mice." (PMID 26115037, 2015). "Esophageal mucosa from a third patient offered an opportunity to map areas of high and low CTSB activity in the same portion of tissue excised from the margin region of the tumor." (PMID 26197973, 2015). "We and others have shown increased cathepsin B secretion and tumor cell invasion in response to factors within the tumor microenvironment including acidic pHe and HGF." (PMID 24505328, 2014). "At the tumor the mask is removed by CTSB, a ubiquitous proteolytic enzyme that is so destructive to tissue that normally it occurs only within cells, encased in lysosomes." (PMID 24588871, 2014). "The mechanism linking AGR2 to tumor invasion and metastasis is involved in several molecular alterations such as CTSB and CTSD." (PMID 24717913, 2014).
tumor (continued). "Rab7 acts as a negative regulator of cell surface-directed lysosome trafficking, cathepsin B secretion, and tumor cell invasion." (PMID 24505328, 2014). "Only mice with excluded expression of both cathepsin B and Cat X exhibited significantly lower tumour growth and metastasis formation." (PMID 24725597, 2014). "Only tumor cells secrete CTSB externally, confined to their plasma membranes, for the purpose of penetrating basement membrane and extracellular barriers as they spread." (PMID 24588871, 2014). "This work aimed to synthesize a cathepsin B (CTSB)-cleavable tumor-targeting prodrug peptide doxorubicin (PDOX) and study the in vivo efficacy and toxicities on an animal model of gastric peritoneal carcinomatosis (PC)." (PMID 24588871, 2014). "The increase in cathepsin B activity is directly proportional to the amount of cathepsin B secreted from the tumor cells." (PMID 24505328, 2014). "Cathepsin B (CTSB) is a lysosomal protease that has been shown to promote local tumor invasion and distant metastasis of PDA." (PMID 25050350, 2014). "This system leverages a unique property of the lysosomal protease CtsB, namely that it is specifically translocated to the extracellular milieu of the tumor microenvironment during cancer progression." (PMID 24975267, 2014). "The construct was thus designed for the selective targeting of CtsB-overexpressing tumor and stromal cells in the tumor microenvironment." (PMID 24975267, 2014). "The RAS pathway target genes LOXL2, SPARC and CTSB exert functions in the remodelling of the extracellular matrix, thereby favouring invasion and metastasis of tumour cells." (PMID 24875049, 2014). "CTSB and CTSD contribute to tumor cell invasion and angiogenesis and are commonly associated with metastasis." (PMID 24717913, 2014). "The proteomic study performed on conditioned media from primary tumor cells and differentiated macrophages revealed a high level of extracellular CtsB secreted by both tumor cells and dBMMs." (PMID 24975267, 2014). "Here the effect of tumour type and tumour size on EPR-mediated tumour localisation and cathepsin B-mediated drug release was studied." (PMID 23797686, 2013). "Tumour cells secreted procathepsin B and both active forms of cathepsin B and cysteine protease inhibitors." (PMID 23986888, 2013). "Among these identified proteins, CTSB was up-regulated 5.0-fold in tumor compared with pair adjacent normal tissue (P < 0.05)." (PMID 24139065, 2013). "To address tumor biological processes affected by CTSB-shRNA, we investigated proliferation and apoptosis in vivo by PCNA IHC analysis and TUNEL assay." (PMID 24139065, 2013). "In glioma cell lines, CTSB knockdown inhibits tumor-induced angiogenesis by modulating the expression of vascular endothelial growth factor (VEGF)." (PMID 22384200, 2012). "Expression of GLUT-1, EGFR, MMP-9 and Cathepsin B was found throughout the tumor and the expression patterns closely corresponded to those obtained with FLI." (PMID 22348134, 2012). "Proteins including matrix metalloproteinase-9 (MMP9), cathepsin B, matrilysin, and laminin have been identified as being highly expressed in tumor budding." (PMID 22919486, 2012). "Sensitivity to CA-074 also characterizes other tumor cell lines indicating preference for cathepsin-B in hypericin mediated HIF-1α turnover." (PMID 21949677, 2011). "In the IBC tissues, we observed strong expression of cathepsin B in tumor cells and in tumor emboli within dermal lymphatics and moderate expression in stromal cells." (PMID 22093547, 2011). "Secreted human cathepsin B is known to degrade extracellular matrix proteins in human tissue, where it has been reported to facilitate tumor invasion and metastasis." (PMID 21980548, 2011). "Much work has been done on the collagenolytic abilities of cathepsin B and its role in tumor metastasis by degrading the basement membrane of tumor cells, but it has an occluding loop that makes its structure quite different from cathepsins K, L, and S." (PMID 21756348, 2011).
tumor (continued). "Furthermore, cysteine cathepsins, and in particular cathepsin B, are considered to be involved in malignancies and cancer progression due to an increase in expression and activity in cancer cells as well as due to increased secretion from tumor-associated cells." (PMID 21835049, 2011). "Of IBC tumor cells that express cathepsin B (score of ++ or +++), 70% also expressed caveolin-1 (score of ++ or +++), whereas only 19% of non-IBC tumor cells showed this co-expression (P = 0.001)." (PMID 22093547, 2011). "A correlation between cathepsin B mRNA expression in TAM with NSCLC tumor T status was found (p = 0.037)." (PMID 21595995, 2011). "The 12-lipoxygenase metabolite of arachidonic acid that can up-regulates surface expression of integrins, induces secretion of cathepsin-B from tumor cells." (PMID 21321384, 2010). "Cathepsin-B (CTS-B) and Cathepsin–S (CTS-S) are cysteine proteases and have been implicated in ECM remodeling, in particular in processes important for tumor development and progression, including angiogenesis, cell proliferation and invasion." (PMID 21321384, 2010). "Several studies have convincingly demonstrated that cystatin C is an important inhibitor of cathepsin B and tumor cell invasion." (PMID 19956729, 2009). "CK18, CK8 and cathepsin B were involved in cell malignant transformation and the destruction of basement membranes by degrading collagen and laminin, promoting tumor migration." (PMID 19216771, 2009). "We demonstrated that genetic ablation of cathepsin B results in suppression of tumor infiltrating pro-inflammatory cells, notable attenuation of polyposis, and a decrease in the fluorescent signal emanating from the lesions." (PMID 18698347, 2008). "Cathepsins of the cysteine protease family and in particular cathepsin-B are commonly active in the tumor microenvironment, contributing to the regulation of angiogenesis and invasion during cancer progression." (PMID 18698347, 2008). "HPMA copolymer-cathespin B exhibited a longer plasma half-life (free cathepsin B t1/2α= 2.8 h; bound cathepsin B t1/2α= 3.2 h) and a 4.2-fold increase in tumour accumulation compared to the free enzyme." (PMID 11592781, 2001). "In the tumor context, direct targeting of the A77/G198 sites of tissue protease B (CTSB) can block the lysosomal pathway of tumor cells responsible for MHC-I degradation, thus increasing the surface abundance of MHC-I to enhance the recognition and cytotoxicity of CD8+ T cells." (PMID 41601951, 2026). "The genes most positively associated with TMBIM6 expression, including LAMP2, APLP2, TMED10, PPAPDC2, ZNF652, and CTSB, are primarily involved in lysosomal and ER trafficking, membrane dynamics, and metabolic resilience—pathways that facilitate tumor survival under cellular stress conditions." (PMID 41516091, 2025). "Cathepsin B serine protease is involved in extracellular matrix remodeling and tumor invasion." (PMID 40191195, 2025). "While cathepsin B promotes extracellular matrix degradation, cystatin C may act as a compensatory response aimed at limiting tumor progression." (PMID 41149076, 2025). "On the other hand, the resistance of tumor cells to the cytotoxic effect of lymphocytes may result from the degradation of perforin by cathepsin B, a lysosomal peptidase expressed on the surface of lymphocytes after degranulation." (PMID 40766321, 2025). "By conjugating drugs to the dendrimer periphery via peptide linkers that are susceptible to cleavage by enzymes overexpressed in the tumor microenvironment (e.g., cathepsin B cleaving the Gly-Phe-Leu-Gly sequence), controlled drug release specifically at the tumor site can be achieved." (PMID 40564134, 2025). "Collectively, our study is the first to describe the molecular mechanisms underlying the biological activity of BEA against human CTSB, suggesting that CTSB may be a candidate target for tumor therapy." (PMID 40411408, 2025).